PSMC6 (proteasome 26S subunit, ATPase 6)
Description:
Component of the 26S proteasome, a multiprotein complex involved in the ATP-dependent degradation of ubiquitinated proteins. This complex plays a key role in the maintenance of protein homeostasis by removing misfolded or damaged proteins, which could impair cellular functions, and by removing proteins whose functions are no longer required. Therefore, the proteasome participates in numerous cellular processes, including cell cycle progression, apoptosis, or DNA damage repair. PSMC6 belongs to the heterohexameric ring of AAA (ATPases associated with diverse cellular activities) proteins that unfolds ubiquitinated target proteins that are concurrently translocated into a proteolytic chamber and degraded into peptides.
Synonyms: SUG2; p42; RPT5
Tractability: Small molecule: an approved drug acts on it; a structure with a bound ligand is known; a high-quality ligand is known. Antibody: the Human Protein Atlas places it where antibodies can reach. PROTAC: ubiquitination databases record sites on it; its protein half-life has been measured.
Target class: Enzyme
Gene: Protein-coding gene on chromosome 14 (52,707,156 to 52,728,590, forward strand). Ensembl gene ENSG00000100519.
Subcellular location: Cytoplasm; Nucleus
Subcellular location (Human Protein Atlas): Cytosol; Nucleoplasm; Plasma membrane
Pathways (Reactome):
Immune System: AMPK-induced ERAD and lysosome mediated degradation of PD-L1(CD274); Activation of NF-kappaB in B cells; Antigen processing: Ubiquitination & Proteasome degradation; CLEC7A (Dectin-1) signaling; Cross-presentation of soluble exogenous antigens (endosomes); Dectin-1 mediated noncanonical NF-kB signaling; Downstream TCR signaling; ER-Phagosome pathway; FCERI mediated NF-kB activation; GSK3B-mediated proteasomal degradation of PD-L1(CD274); Interleukin-1 signaling; NIK-->noncanonical NF-kB signaling; SPOP-mediated proteasomal degradation of PD-L1(CD274); TNFR2 non-canonical NF-kB pathway
Cell Cycle: APC/C:Cdc20 mediated degradation of Securin; APC/C:Cdh1 mediated degradation of Cdc20 and other APC/C:Cdh1 targeted proteins in late mitosis/early G1; Autodegradation of Cdh1 by Cdh1:APC/C; Autodegradation of the E3 ubiquitin ligase COP1; Cdc20:Phospho-APC/C mediated degradation of Cyclin A; FBXL7 down-regulates AURKA during mitotic entry and in early mitosis; G2/M Checkpoints; SCF(Skp2)-mediated degradation of p27/p21; SCF-beta-TrCP mediated degradation of Emi1; Separation of Sister Chromatids; The role of GTSE1 in G2/M progression after G2 checkpoint; Ubiquitin-Mediated Degradation of Phosphorylated Cdc25A; Ubiquitin-dependent degradation of Cyclin D
Signal Transduction: Asymmetric localization of PCP proteins; Degradation of AXIN; Degradation of DVL; Degradation of GLI1 by the proteasome; Degradation of GLI2 by the proteasome; Degradation of beta-catenin by the destruction complex; GLI3 is processed to GLI3R by the proteasome; Hedgehog 'on' state; Hedgehog ligand biogenesis; MAPK6/MAPK4 signaling; Negative regulation of NOTCH4 signaling; Regulation of PTEN stability and activity; Regulation of RAS by GAPs
and 28 more pathways
Gene Ontology:
Molecular function: identical protein binding; protein binding; proteasome-activating activity; protein-macromolecule adaptor activity; ATP binding; ATP hydrolysis activity
Biological process: cellular response to type I interferon; ERAD pathway; positive regulation of proteasomal protein catabolic process; positive regulation of RNA polymerase II transcription preinitiation complex assembly; proteasomal protein catabolic process; proteasome-mediated ubiquitin-dependent protein catabolic process; regulation of proteasomal protein catabolic process; response to oxidative stress; positive regulation of inclusion body assembly
Cellular component: extracellular exosome; membrane; nucleus; proteasome complex; cytosol; nucleoplasm; proteasome accessory complex; synaptic vesicle; cytoplasm; cytosolic proteasome complex; inclusion body
Genetic constraint (gnomAD): Loss-of-function variants: 3 observed, 41.99 expected, observed/expected ratio (o/e) 0.0714, 90% interval 0.032 to 0.19. The upper end of that interval is the gene's LOEUF score, 0.19, which puts it in group 1 of 6, group 1 being the genes least tolerant of losing a copy. Missense variants: 187 observed, 409.08 expected, observed/expected ratio (o/e) 0.46, 90% interval 0.41 to 0.52. Synonymous variants: 117 observed, 135.99 expected, observed/expected ratio (o/e) 0.86, 90% interval 0.74 to 1.
Homologues: Orthologues: dog PSMC6 (100% identical), guinea pig PSMC6 (100% identical), mouse Psmc6 (100% identical), rabbit PSMC6 (100% identical), rat Psmc6 (100% identical), tropical clawed frog psmc6 (99% identical), zebrafish psmc6 (97% identical), Drosophila melanogaster Rpt4 (89% identical), pig PSMC6 (88% identical), Caenorhabditis elegans rpt-4 (82% identical), Drosophila melanogaster Rpt4R (82% identical). Paralogues in human: PSMC2 (46% identical), PSMC5 (44% identical), PSMC4 (41% identical), PSMC1 (41% identical), PSMC3 (40% identical).